HNRNPH1 (heterogeneous nuclear ribonucleoprotein H1)
Diseases named in the same sentence as HNRNPH1 in open-access papers (continued):
Sharing a sentence is not in itself a finding about the gene and the disease.
tumor (continued). "HNRNPH1 and CLK1, two trans-acting splicing regulator factors, are predicted by our computational analysis to be differentially spliced between tumor cells." (PMID 20700505, 2010). "At the molecular level, the juxtaposition of HNRNPH1 and SOX11 super-enhancers to MYC cis-regulatory elements, through a mechanism of distance looping, appears to be responsible for MYC overexpression and the abnormal proliferation of group 3 tumor cells." (PMID 37568705, 2023). "HNRNPH1 is overexpressed in malignant cells, especially in the neural- and oligodendrocyte-progenitor-like state, and its expression levels are higher in non-hypoxic regions of the tumor." (PMID 41872153, 2026). "In accordance with our hypothesis and with the published data, tumor tissue from CRC patients revealed an increase in hnRNPH1 expression when compared to nontumorous tissue." (PMID 36611995, 2023). "Indeed, we found that HNRNPH1 levels were not downregulated in terminal tumor samples after a prolonged time of doxycycline treatment." (PMID 29362363, 2018). "Four SFs were not significantly different between matched normal and tumor samples (CDC40, HNRNPH1, HNRNPCL1, and HNRNPM)." (PMID 37531400, 2023). "Proteins that were perturbed in expression level in the peripheral or in the central part of the tumor as compared with the non-involved part included S100A11, HNRNPF, HNRNPH1 or HNRNPH2, GSTP1, PKM and FABP1." (PMID 34563043, 2021). "An inverse correlation between hnRNPH1 and caspase-7 was confirmed in HCT-15 cells but also in HEK293 cells, which indicates that the inverse correlation between both proteins is not exclusively found in tumor cells." (PMID 36611995, 2023). "Furthermore, the authors of the study found that hnRNPH1 did not influence SGPL1 expression in non-tumorous cells, implying that the hnRNPH1 regulation of target mRNA is rather a tumor-specific phenomenon." (PMID 36611995, 2023).
cancer (25 papers, 2016 to 2025). A tumor composed of atypical neoplastic, often pleomorphic cells that invade other tissues. "Our analysis of specific splicing events highlights how the abundance of HNRNPH1 in cancer or the disruption of its function via mutation could contribute to alterations in the variety and/or abundance of specific protein isoforms." (PMID 40766465, 2025). "Regarding translational regulation, although direct evidence in cancer is limited, the roles of hnRNPH1 in other systems suggest several potential mechanisms." (PMID 40507967, 2025). "hnRNPH1 exerts complex and often pro-tumorigenic functions during the development and progression of numerous cancers." (PMID 40507967, 2025). "Here, we systematically discussed the structural basis and core molecular functions of hnRNPH1, and elucidated its mechanisms and pathological significance in cancer, neurological disorders, reproductive system disorders, and other non-oncological diseases." (PMID 40507967, 2025). "This suggests that hnRNPH1 employs similar mechanisms to regulate the translation of cancer-related genes." (PMID 40507967, 2025). "In cancer, hnRNPH1 contributes to leukemia progression through PI3K/AKT pathway modulation and PTPN6 regulation." (PMID 40507967, 2025). "Genes frequently mutated or exhibiting altered methylation in favorable prognosis cases were enriched in the MAPK pathway, suggesting a potential protective role for hnRNPH1 in this specific cancer type." (PMID 40507967, 2025). "Our sequencing results for WDR81 and HNRNPH1 are consistent with the mRNA expression interval of the CCLE pan-cancer spectrum results." (PMID 36593250, 2023). "We also included four additional splicing regulatory genes (HNRNPA2B1, HNRNPH1, HNRNPCL1, and SRPK1) because they are either related to cancer in general or have been associated with telomere biology (HNRNPA2B1:; HNRNPH1:; HNRNPCL1:; SRPK1:)." (PMID 37531400, 2023). "HNRNPH1, a core member of the heterogeneous nuclear ribonucleo-proteins family, frequently upregulated in various cancer cells and contributed to tumorigenesis." (PMID 36514015, 2022). "The splicing factor HNRNPH1 was reported to inhibit apoptosis in cancer cells partially by regulating the A-Raf kinase in the mitogen-activated protein kinase pathway." (PMID 27279334, 2016). "Although the precise mechanisms remain unclear, studies suggest that hnRNPH1 plays a key role in maintaining neuronal RNA homeostasis, and its cancer-related pro-survival functions might paradoxically contribute to the pathology of neurodegeneration." (PMID 40507967, 2025). "HNRNPH1 is frequently upregulated in multiple cancer cells and involved in tumorigenesis." (PMID 36681772, 2023). "Similarly, HNRNPH1 participates in RNA editing, modification and stability, is a regulator of cellular proliferation, and is frequently upregulated in cancers." (PMID 38161589, 2023). "However, other evidence indicates that HNRNPH1 can localize to the cytoplasm in cancer cells, suggesting the possibility of interaction between HNRNPH1 and LINC00662." (PMID 34148056, 2021). "Therefore, by using the Flag-MS2bp-MS2bs-based system and, subsequently, mass spectrometry examination, hnRNPH1 was pulled down in this process, and the result was validated in four other cancer cell lines." (PMID 30999914, 2019). "Thus, we propose that hnRNPH1 mediates pre-ITPR1 splicing in human cancer by binding these GGGA/C/G motifs." (PMID 30999914, 2019). "Several RBPs exhibited widespread activities in various cell types and cancer types, such as HNRNPH3, HNRNPH1 and TIAL1." (PMID 36681772, 2023). "We previously analyzed the expression levels of HNRNPF and HNRNPH1 or HNRNPH2 on normal and several types of cancer tissues." (PMID 34563043, 2021).
cancer (continued). "The eosinophil granule ontogeny transcript (lncRNA EGOT) recruits heterogeneous nuclear ribonucleoprotein H1 (hnRNPH1) to enhance the alternative splicing of pre-inositol 1,4,5-trisphosphate receptor type 1 (ITPR1) to promote autophagy in human cancer." (PMID 32429086, 2020). "In addition, three other proteins analyzed in this study, HNRNPH1, TRA2A, and SRSF6, were found to be involved in cancer development in previous studies." (PMID 39023715, 2024). "EGOT can directly bind to the cis-acting element in ITPR1 pre-mRNA, resulting in the recruitment of the SF hnRNPH1 to promote hnRNPH1-mediated AS, contributing to the expression of the ITPR1 protein, which sensitizes cells to paclitaxel cytotoxicity in cancer therapy." (PMID 33407694, 2021). "While hnRNPH2 and hnRNPH1 have not been considered for cancer drug discovery, there are molecules that bind other spliceosomal components that are being investigated for cancer therapy." (PMID 31573152, 2019).
infection (7 papers, 2013 to 2024). The state of being infected such as from the introduction of a foreign agent such as serum, vaccine, antigenic substance or organism. "In this study, we found that hnRNPH1 only binds the vRNA of the influenza virus in the nucleus at the early stage of infection, after 24 h post-infection." (PMID 39858792, 2024). "Given that the vRNPs of influenza viruses are localized in the nucleus during the early stage of infection, the co-localization of hnRNPH1 and vRNPs was checked in infected cells." (PMID 39858792, 2024).
neurodevelopmental disorder (5 papers, 2023 to 2025). A behavioral and cognitive disorder with onset during the developmental period that involves impaired or aberrant development of intellectual, motor, or social functions. "As an example, we present HNRNPH1-227, a hub IR node (degree ≥10) in both networks and a known transcription and splicing factor associated with neurodevelopmental disorders." (PMID 40927681, 2025). "This, in turn, inhibits the expression of pro-differentiation factors like TRF2-s, providing a molecular basis for the phenotypic diversity observed in hnRNPH1-related neurodevelopmental disorders." (PMID 40507967, 2025). "In pathological states, hnRNPH1 mutations or functional abnormalities can lead to impaired RBM3 expression, weakening neuronal defenses against degenerative insults, a phenomenon with mechanistic similarities to the splicing dysregulation triggered by hnRNPH1 defects in neurodevelopmental disorders." (PMID 40507967, 2025).
neurodegenerative disease (2 papers, 2023 to 2025). A disorder of the central nervous system characterized by gradual and progressive loss of neural tissue and neurologic function. "In the nervous system, hnRNPH1 is involved in neurodevelopment, neurodegenerative diseases, and drug addiction and plays an essential role in maintaining neuronal function and homeostasis." (PMID 40507967, 2025). "In neurodegenerative diseases, hnRNPH1 dysfunction shares pathological parallels with other RBPs implicated in these conditions, such as TDP-43 and FUS, which are involved in RNA metabolism disturbances and abnormal protein aggregation." (PMID 40507967, 2025). "By developing inhibitors targeting these modifications (e.g., SRPK1 inhibitors), it is possible to effectively modulate hnRNPH1 function and show the potential for treating tumors and neurodegenerative diseases." (PMID 40507967, 2025). "In summary, hnRNPH1 appears to play a dual role in neurodegenerative diseases, and its dysfunction can exacerbate neuronal injury through RNA dysmetabolism and proteotoxicity, while also exhibiting neuroprotective potential via the regulation of factors such as RBM3." (PMID 40507967, 2025).
cardiovascular diseases (1 paper, 2025). "In the cardiovascular system, hnRNPH1 influences the expression of cardiovascular disease-related genes by recognizing G-rich RNA sequences and regulating RNA splicing and stability." (PMID 40507967, 2025). "Moreover, the roles of hnRNPH1 in reproductive system disorders, cardiovascular diseases, and immune-related conditions merit further exploration, potentially yielding new targets and strategies for disease prevention and treatment." (PMID 40507967, 2025).
hematological malignancies (1 paper, 2024). "Mutations in splicing factors, such as U2AF1, SF3B1, SRSF2, ZRSR2, and HNRNPH1, are frequently observed across various hematological malignancies and are associated with poor prognosis and treatment resistance." (PMID 39584923, 2024).
HNRNPH1 also shares sentences with these, for which no sentence is quoted: Cirrhosis (4 papers); lung carcinoma (2); autism (1); chronic hepatitis (1); connective tissue diseases (1); endometrial cancer (1); esophageal cancer (1); glioblastoma (1); head and neck squamous cell carcinoma (1); hypospadias (1); ischemia (1); lung squamous cell carcinoma (1); microphthalmia (1); myotonic dystrophy type 1 (1); non-small cell lung carcinoma (1); ovarian serous cystadenocarcinoma (1); pancreatic cancer (1); reproductive system disorder (1); systemic lupus erythematosus (1); teratoma (1).